NIPA2 (NIPA magnesium transporter 2)
Description:
Acts as a selective Mg(2+) transporter.
Synonyms: SLC57A2
Tractability: Antibody: UniProt places it where antibodies can reach, with high confidence; its Gene Ontology location is reachable by antibodies, with high confidence; UniProt predicts a signal peptide or a membrane-spanning region.
Gene: Protein-coding gene on chromosome 15 (22,838,625 to 22,869,362, forward strand). Ensembl gene ENSG00000140157.
Subcellular location: Cell membrane; Early endosome
Subcellular location (Human Protein Atlas): Golgi apparatus
Pathways (Reactome):
Transport of small molecules: Miscellaneous transport and binding events
Gene Ontology:
Molecular function: magnesium ion transmembrane transporter activity
Biological process: magnesium ion transport; magnesium ion transmembrane transport
Cellular component: plasma membrane; early endosome; membrane
Genetic constraint (gnomAD): Loss-of-function variants: 6 observed, 17.15 expected, observed/expected ratio (o/e) 0.35, 90% interval 0.19 to 0.69. The upper end of that interval is the gene's LOEUF score, 0.69, which puts it in group 2 of 6, group 1 being the genes least tolerant of losing a copy. Missense variants: 325 observed, 332.55 expected, observed/expected ratio (o/e) 0.98, 90% interval 0.89 to 1.07. Synonymous variants: 127 observed, 123.51 expected, observed/expected ratio (o/e) 1.03, 90% interval 0.89 to 1.19.
Homologues: Orthologues: chimpanzee NIPA2 (99% identical), macaque NIPA2 (99% identical), pig NIPA2 (99% identical), dog NIPA2 (98% identical), rabbit NIPA2 (97% identical), rat Nipa2 (96% identical), mouse Nipa2 (96% identical), tropical clawed frog nipa2 (84% identical), zebrafish nipa2 (81% identical), guinea pig Nipa2 (36% identical). Paralogues in human: NIPAL1 (65% identical), NIPAL4 (58% identical), NIPA1 (37% identical), NIPAL2 (26% identical), NIPAL3 (23% identical).
Diseases named in the same sentence as NIPA2 in open-access papers:
NIPA2 is named in the same sentence as 32 diseases in open-access papers, as found by Europe PMC text mining. Sharing a sentence is not in itself a finding about the gene and the disease. The quoted sentences say what the papers report.
Angelman syndrome (8 papers, 2008 to 2025). A neurogenetic disorder characterized by severe intellectual deficit and distinct facial dysmorphic features. "This region covered the TUBGCP5, CFYIP1, NIPA1 and NIPA2 genes, which were critical genes causing behavioral and academic differences in the Prader-Willi/Angelman syndrome." (PMID 38784233, 2024). "The less frequent microdeletion 15q11.2, containing four protein-coding genes (NIPA1, NIPA2, CYFIP1, and TUBGCP5), is associated with Burnside–Butler syndrome (BBS), which partially overlaps with certain neurodevelopmental disorders, including Prader-Willi and Angelman syndrome." (PMID 36553064, 2022). "It is adjacent to the Parder–William/Angelman syndrome imprinting area, and its size is approximately 500 kb, involving four OMIM genes: NIPA1, NIPA2, CYFIP1, and TUBGCP5, which are hot spots in clinical research." (PMID 38172840, 2024). "Previous study has found that non-imprinted protein 2 in the Prader-Willi/Angelman syndrome region (NIPA2), a mitophagy-related molecule, was decreased in the bone tissue of diabetic mice." (PMID 39758822, 2025).
autism (8 papers, 2012 to 2023). Persistent deficits in social interaction and communication and interaction as well as a markedly restricted repertoire of activity and interest as well as repetitive patterns of behavior. "In silico analyses for the four coding genes of NIPA1, NIPA2, CYFIP1, and TUBGCP5 in the 15q11.2 region suggested cardinal disease associations of NIPA1‐Spastic paraplegia 6, NIPA2‐PWS/AS, CYFIP1‐fragile X syndrome and autism, and TUBGCP5‐AS." (PMID 37013615, 2023). "Moreover, 7 SNPs (rs3812922 in NIPA2, rs8037745 in SNRPN, rs4906771 and rs1345098 in ATP10A, rs12438141, rs1863467, and rs4906902 in GABRB3) displayed nominal association with autism under the additive model in our samples (p < 0.05)." (PMID 30108208, 2018). "Nine SNPs (rs8025849 in NIPA1, rs3812922 in NIPA2, rs1009153 and rs2289818 in CYFIP1, rs8037745 in SNRPN, rs12438141 and rs1863467 in GABRB3, rs7403021 and rs7180500 in GABRG3) were nominally associated with autism under the recessive model (p < 0.05)." (PMID 30108208, 2018).
epilepsy (5 papers, 2012 to 2025). A brain disorder characterized by episodes of abnormally increased neuronal discharge resulting in transient episodes of sensory or motor neurological dysfunction, or psychic dysfunction. "If a drug could rescue NIPA2‐induced pathogenic process, then this drug would save patients with epilepsy." (PMID 30895737, 2019). "Zonisamide, reducing action potential firing in NIPA2‐knockout mice, is probably a potential treatment for NIPA2 mutation‐induced epilepsy, which may provide a basis for the development of new treatment strategies for epilepsy." (PMID 30895737, 2019). "Zonisamide is probably a potential treatment for NIPA2 mutation‐induced epilepsy, which may provide a basis for the development of new treatment strategies for epilepsy." (PMID 30895737, 2019). "We believe that zonisamide is probably a potential treatment for NIPA2 mutation‐induced epilepsy." (PMID 30895737, 2019). "Zonisamide may be used to treat the epilepsy patients with NIPA2 loss‐of‐function mutation." (PMID 30895737, 2019). "Zonisamide, an anti‐epilepsy drug, reduced action potential firing in NIPA2‐knockout mice through increasing BK channel currents." (PMID 30895737, 2019). "The NIPA2 gene encoded protein plays an important role in the transport of Mg2+ in the kidneys and is overexpressed in B lymphocytes and the placenta, which is associated with Parder–William syndrome, ASD, and epilepsy." (PMID 38172840, 2024).
childhood absence epilepsy (3 papers, 2014 to 2020). A familial generalized pediatric epilepsy, characterized by very frequent (multiple per day) absence seizures, usually occurring in children between the ages of 4 and 10 years, with, in most cases, a good prognosis. "Mutations in the NIPA2 gene have been reported in generalized epilepsy and childhood absence epilepsy." (PMID 32384786, 2020). "Moreover, mutations in each gene were associated with different disorders: NIPA1 with autosomal-dominant hereditary spastic paraplegia, NIPA2 with childhood absence epilepsy, TUBGCP5 with ADHD and obsessive-compulsive disorder, and CYFIP1 with increasing susceptibility to ASD and with schizophrenia." (PMID 30583851, 2019).
developmental delays (3 papers, 2020 to 2025). "The copy number variation (CNV) of 15q11.2, an emerging and common condition observed during prenatal counseling, is encompassed by four highly conserved and non-imprinted genes—TUBGCP5, CYFIP1, NIPA1, and NIPA2—which are reportedly related to developmental delays or general behavioral problems." (PMID 34680874, 2021).
type 2 diabetes (3 papers, 2020). "This research aimed to further our understanding of the possible pathological mechanisms underlying type 2 diabetes osteoporosis by investigating the potential interaction among NIPA2, mitophagy and osteoblast function to develop potential target treatments." (PMID 32080264, 2020). "Therefore, our study was performed to determine the effect of intracellular magnesium deficiency induced by NIPA2 deletion on type 2 diabetes osteoporosis and to investigate the possible pathological mechanism." (PMID 32080264, 2020). "We speculated that deletion of NIPA2 leads to a deficiency in intracellular magnesium, which may affect osteoblast function by modulating mitophagy in type 2 diabetes osteoporosis." (PMID 32080264, 2020). "The highly selective magnesium transporter non-imprinted in Prader-Willi/Angelman syndrome region protein 2 (NIPA2) has recently been associated with the development and progression of type 2 diabetes osteoporosis, but the mechanisms involved are still poorly understood." (PMID 32080264, 2020). "Downregulation of the highly selective magnesium transporter NIPA2 in bone tissues and osteoblasts of type 2 diabetes osteoporosis was highlighted for the first time in our in vivo experiments." (PMID 32080264, 2020). "But few researches showed the relationship between NIPA2 and mitophagy in type 2 diabetes osteoporosis." (PMID 32080264, 2020). "Because mitophagy is involved in the pathology of type 2 diabetes osteoporosis, the present study aimed to explore the relationship among NIPA2, mitophagy and osteoblast osteogenic capacity." (PMID 32080264, 2020). "Taken together, these results suggest that NIPA2 positively regulates the osteogenic capacity of osteoblasts via the mitophagy pathway in type 2 diabetes." (PMID 32080264, 2020). "We found that the absence of NIPA2 in osteoblasts leads to deficiency of intracellular magnesium under type 2 diabetes environment." (PMID 32080264, 2020). "Therefore, the expression of NIPA2 in a widely used T2DM model, db/db mice and in vitro models of type 2 diabetes osteoporosis were examined, and the level of mitophagy in high glucose (HG)-treated hFOB1.19 osteoblasts was analyzed." (PMID 32080264, 2020). "Although magnesium and mitophagy play critical roles in the process of osteoporosis, the interaction of magnesium transporter NIPA2 and mitophagy in type 2 diabetes osteoporosis is not known." (PMID 32080264, 2020). "NIPA2 expression was reduced in C57BKS background db/db mice and in vitro models of type 2 diabetes osteoporosis, and the activation of mitophagy in primary culture osteoblast-derived from db/db mice and in high glucose-treated human fetal osteoblastic cells (hFOB1.19) was observed." (PMID 32080264, 2020). "Furthermore, an epidemiological study showed a genetic variation of NIPA2 in T2DM12, but few studies have provided experimental evidence of the relationship between NIPA2 and type 2 diabetes osteoporosis, and the specific mechanism is still unclear." (PMID 32080264, 2020).
Intellectual disability (2 papers, 2020 to 2023). "Both proband 15, a boy affected by TS, OCD, behavioral problems, and mild dysmorphic features, and proband 19, a girl affected by TS, mild intellectual disability, and ODD, presented the recurrent 15q11.2 deletion of about 395 Kb, which includes TUBGCP5, CYFIP1, NIPA1, and NIPA2 genes." (PMID 36833427, 2023).
depression (1 paper, 2021). "The DMRs were located at/near 19 genes, among which DGKA and NIPA2 might play an important roles in regulating depression." (PMID 34341332, 2021).
Sepsis (1 paper, 2025). Sepsis is defined as life-threatening organ dysfunction caused by a dysregulated host response to infection. "Only a small number of host genes were differentially expressed between the Gram-positive (HLA-B, SERPINB10, LOC105377885, CEACAM6, NIPA2) and Gram-negative (CBFA2T3, LOC107987303, MARCO) sepsis samples in our cohort." (PMID 40965975, 2025).
neurodevelopmental disorder (4 papers, 2012 to 2024). A behavioral and cognitive disorder with onset during the developmental period that involves impaired or aberrant development of intellectual, motor, or social functions. "In this study, we explored functions and interactions of the four protein-coding genes in this region, namely NIPA1, NIPA2, CYFIP1, and TUBGCP5, and elucidate their role, in solo and in concert, in the causation of neurodevelopmental disorders." (PMID 32384786, 2020). "Some of these genes themselves are of interest in brain development specifically, Nipa2 (non-imprinted in Prader-Willi/Angelman syndrome 2), Sez6 (seizure-related 6 homologs), and Aff4 (AF4/FMR2 family member 4) are involved in neurodevelopmental disorders with complex phenotypes." (PMID 37059894, 2024).
brain disorder (1 paper, 2021). A disease affecting the brain or part of the brain. "In addition, three of the four genes (CYFIP1, NIPA1, and NIPA2) have been shown to play a role in neurodevelopment and are associated with brain disorders." (PMID 34970295, 2021).
NIPA2 also shares sentences with these, for which no sentence is quoted: fragile X syndrome (3 papers); attention deficit-hyperactivity disorder (2); autism spectrum disorder (2); generalized epilepsy (2); obsessive-compulsive disorder (2); osteoporosis (2); absence seizures (1); congenital heart disease (1); developmental disabilities (1); Dyscalculia (1); dyslexia (1); idiopathic generalized epilepsies (1); microcephaly (1); paraplegia (1); Prader-Willi syndrome (1); psychosis (1); rhabdoid tumor (1); schizophrenia (1); Spastic paraplegia (1); Spastic paraplegia 6 (1); temporal lobe epilepsy (1).